DPP4 (dipeptidyl peptidase 4)
Diseases named in the same sentence as DPP4 in open-access papers (continued):
Sharing a sentence is not in itself a finding about the gene and the disease.
Insulin resistance (continued). "DPP-4 inhibitors are also shown to induce autophagy, and these lead to beneficial effects such as cardioprotection, hepatic insulin resistance, or hepatic steatosis." (PMID 32937958, 2020). "Of note, DPP-4 has been shown to regulate inflammation and insulin resistance in the setting of obesity by modulating the macrophage polarity." (PMID 32610588, 2020). "DPP4 also has roles in steatosis, insulin resistance, cancers and inflammatory and fibrotic diseases." (PMID 33218025, 2020). "In the present study, we demonstrated AE attenuate palmitate-induced DPP-4 activation and insulin resistance cascades." (PMID 33267804, 2020). "The present study found that omarigliptin exerted more anti-inflammatory and anti-insulin resistance effects than daily DPP4 inhibitors." (PMID 32211075, 2020). "Our previous report suggested dipeptidyl peptidase-4 (DPP-4) is crucial to insulin resistance, and the subfractions of Abelmoschus esculentus (AE), F1 and F2, attenuate the signaling." (PMID 33267804, 2020). "A recent study has shown that DPP4 secreted by hepatocytes in obese mice promotes adipose inflammation and insulin resistance." (PMID 32211075, 2020). "For instance, it has been reported that DPP-4 inhibitors ameliorate lipid accumulation and insulin resistance in the liver, along with systemic glucose intolerance." (PMID 31969650, 2020). "The results showed that weekly doses of omarigliptin decreased hsCRP and remnant lipoproteins and ameliorated insulin resistance more effectively than daily doses of the other two DPP4 inhibitors." (PMID 32211075, 2020). "However, since T2D is associated with dyslipidemia, hypertension and insulin resistance, part of which are ameliorated by DPP-4 inhibitors, it remains unclear whether DPP-4 inhibitors could have anti-atherosclerotic properties directly by attenuating the harmful effects of hyperglycemia." (PMID 32646003, 2020). "Groups were well balanced in terms of DPP4 inhibitor use, glucose metabolism and insulin resistance." (PMID 31729622, 2020). "DPP-4 levels are positively correlated with BMI and insulin resistance and, in some studies, also to glycaemic control, but the mechanisms regulating synthesis and release of DPP-4 are still incompletely understood." (PMID 30828317, 2019). "BAI and HOMA-IR exerted the more significant effect on DPP4 activity, reassuring the existence of a role derived from body fat and insulin resistance in the plasma DPP4 activity of subjects with excessive adiposity." (PMID 30886868, 2019). "Our previous report showed that Hibiscus sabdariffa polyphenols (HPE) improved insulin sensitivity by attenuating DPP-4 and the downstream signals in the palmitate-induced model displaying insulin resistance." (PMID 31237881, 2019). "Hepatic steatosis improvement by SGLT2is has been linked to the inhibition of serum soluble dipeptidyl peptidase 4 (DPP4) enzyme secreted by hepatocytes and insulin resistance." (PMID 31328066, 2019). "Our previous study have shown that DPP-4 mediate the insulin resistance signals and the downstream cascades." (PMID 31237881, 2019). "Yet other studies have pointed toward DPP-4 acting as a hepatokine, linking the liver and adipose tissue with the development of insulin resistance, and glucose intolerance." (PMID 30828317, 2019). "GLP-1 as well as GIP are rapidly inactivated by the enzyme, DPP4, whose activity correlates with insulin resistance in type 2 DM." (PMID 30360455, 2018). "Sitagliptin and other DPP4 inhibitors are known to act as anti-diabetic agents reversing insulin resistance." (PMID 28118607, 2017). "The longer-term effects of DPP-4 inhibitor treatment on beta-cell function and insulin resistance in patients with T2DM warrant further investigation." (PMID 28322294, 2017). "In an in vitro experiment, DPP4 inhibited insulin-induced Akt phosphorylation, thus linking DPP4 levels to insulin resistance (IR)." (PMID 28450900, 2017).
Insulin resistance (continued). "Metformin primarily ameliorates insulin resistance, whereas DPP-4 inhibitors improve pancreatic islet cell function by maintaining the bioactivity of endogenous GLP-1." (PMID 29057274, 2017). "The strong inhibition of DPP4 protease activity by hypoxia and the insulin-mediated increase in DPP4 indicate that DPP4 represents an important marker for early detection of insulin resistance." (PMID 26881257, 2016). "DPP4 signaling has been shown to decrease phosphorylation of Akt and lead to insulin resistance in adipocytes." (PMID 27213360, 2016). "The increase in DPP4 levels and expression correlates with the degree of glycemia/insulin resistance, suggesting that DPP4 mediated incretin degradation is involved in the pathogenesis of T2DM." (PMID 26075284, 2015). "A growing body of evidence both from clinical and preclinical findings supports the notion that DPP-4 inhibitors can ameliorate insulin resistance through several pathways." (PMID 26500706, 2015). "Other important mechanisms included presence of insulin resistance, excessive visceral adipose tissue, activity of circulating dipeptidyl peptidase-4 and fatty acid-binding protein-4." (PMID 26369690, 2015). "Indirect markers of IR, such as fasting insulin and homeostasis model assessment to quantify insulin resistance (HOMA-IR), were positively associated with DPP4 expression in visceral adipose tissue (VAT) macrophages." (PMID 26146634, 2015). "We have recently demonstrated that DPP4 expressed on adipose tissue macrophages is involved in inflammation and insulin resistance by interacting with ADA." (PMID 26075284, 2015). "DPP4 activity is an important predictor of the onset of insulin resistance and metabolic syndrome in apparently healthy Chinese men and women." (PMID 24647445, 2014). "In fact, treatment with a DPP4 inhibitor, sitagliptin, improves insulin resistance and increases cardiac GLUT4 protein and mRNA abundance in spontaneously hypertensive rats." (PMID 24521405, 2014). "DPP-4 inhibitors are known to augment beta-cell function; however, their effects on insulin resistance (sensitivity) remain uncharacterized." (PMID 24883155, 2014). "In multiple linear regression analysis, baseline DPP4 activity was an independent predictor of an increase in insulin resistance over a 4-year period (P<0.01)." (PMID 24647445, 2014). "In our study, we demonstrated for the first time that baseline plasma DPP4 activity was an independent predictor of an increase in insulin resistance in population-based prospective study." (PMID 24647445, 2014). "The rate of DPP4 release was also significantly correlated with MetS phenotypes, such as waist circumference, insulin resistance, high-density lipoprotein (HDL)-cholesterol and triglycerides." (PMID 23379505, 2013). "DPP-4 inhibition attenuates insulin resistance and improves peripheral glucose utilization in humans." (PMID 22761701, 2012). "Our data clearly demonstrated that IL-10-treated adipose stromal cells could be used to alleviate liver glucose gluconeogenesis, insulin resistance, and DPP4 activity in a mouse model of T2DM." (PMID 39125659, 2024). "Polarization of macrophages and lymphocytes toward a pro-inflammatory phenotype can contribute to the progression of insulin resistance, possibly through the renin–angiotensin–aldosterone system, sympathetic activation and incretin modulators (e.g., DPP-4) and immune responses." (PMID 38715129, 2024). "In the future, the injection of IL-10-treated adipose stromal cells could be a novel and promising cell therapy strategy for alleviating insulin resistance, gluconeogenesis, and DPP4 activity in DM." (PMID 39125659, 2024). "Moreover, it has been proposed that DPP-4 triggers inflammation and insulin resistance in adipose and hepatic tissue." (PMID 38192426, 2023). "DPP4 can also impair the insulin signaling pathway, thereby contributing to insulin resistance." (PMID 37525169, 2023).
Insulin resistance (continued). "Interestingly, maternal sitagliptin treatment, a highly selective DPP-4 inhibitor, has been shown to attenuate glucose intolerance and insulin resistance in male offspring rats at weaning." (PMID 37590249, 2023). "To test the necessity of adiposity and peripheral insulin resistance in vivo for elevated enzymatically active, circulating DPP4, we assessed plasma DPP4 activity in HFHC-fed Pemt–/– mice, which are a lean model of hepatomegaly and hepatic steatosis due to disruption in de novo synthesis of choline." (PMID 36472923, 2023). "Our results suggest that the cell therapeutic approach by using nondiabetic plasma-treated SVFs could be a promising strategy to attenuating DPP4 activity, systemic inflammation, and insulin resistance in diabetic patients." (PMID 35883204, 2022). "The increase of IRS-1 phosphorylation at the residue ser307 (p-ser307-IRS-1) and decrease of p-ser473-Akt (p-Akt) are viewed as the insulin resistance markers, and our previous reports suggested dipeptidyl peptidase-4 (DPP-4) mediates insulin resistance, the crucial factor of metabolic syndrome." (PMID 35290413, 2022). "Although whether the insulin resistance signals regulate the lipid metabolism or the converse cannot be defined, our data revealed that DPP-4 plays a critical role and mediates both the insulin resistance and hepatic lipid accumulation." (PMID 35290413, 2022). "Several studies have reported that the circulating DPP-4 level was related to insulin resistance." (PMID 35139864, 2022). "Furthermore, DPP-4 has a higher distribution in visceral fat tissue, contributing to insulin resistance and adipocyte inflammation." (PMID 36289885, 2022). "F1 and F2 prevented cell apoptosis by attenuating DPP-4 and improving the insulin resistance." (PMID 35290413, 2022). "By ameliorating DPP-4, AE could prevent the hepatic lipogenesis, oxidative burden, and the related insulin resistance." (PMID 35290413, 2022). "The independence of the changes in weight and the lack of association with insulin resistance point towards direct involvements of DPP4 independent of the well-described effects on glucose metabolism." (PMID 33538983, 2021). "However, DPP4 can be released from the membrane in response to certain stimuli, such as insulin resistance, tumor necrosis factor-alpha, and chronic low-grade inflammation, resulting in its soluble form." (PMID 34203048, 2021). "Our findings provide a new insight that the inhibition of M1 cytokine expression in adipose tissue may represent a novel therapeutic approach for attenuating DPP4 activity, systemic inflammation, and insulin resistance in diabetic patients." (PMID 34043673, 2021). "Elevated liver expression of DPP4 may promote non-alcoholic fatty liver disease and insulin resistance." (PMID 34298827, 2021). "Since hepatic expression of DPP4 is associated with NAFLD, we examined whether OMG improves liver function as well as levels of inflammation and insulin resistance in type 2 diabetic patients with NAFLD." (PMID 33691757, 2021). "Although the mechanisms how changing from daily DPP4 inhibitors to weekly OMG causes beneficial effect in liver with NAFLD/NASH are unclear, decreasing effect of OMG on inflammation and insulin resistance probably in liver might be involved." (PMID 33691757, 2021). "Several types of antidiabetic drugs, including metformin, glucagon-like peptide-1 receptor agonists and dipeptidyl peptidase-4 inhibitors, were also associated with the normalization of enzyme levels in NAFLD by inhibiting liver inflammation and improving insulin resistance." (PMID 33971815, 2021). "The enzyme dipeptidyl peptidase 4 (DPP-4) can promote insulin resistance." (PMID 35111461, 2021). "Interestingly, we also found that chronic EtOH feeding induced a significant increase in the hepatic expression of DPP‐4, which has been reported to promote insulin resistance and correlate with NAFLD." (PMID 32267550, 2020).
Insulin resistance (continued). "In individual patients with FPLD insulin secretion disruption or low dipeptidyl peptidase 4 (DPP4) levels were observed in addition to insulin resistance, suggesting the use of glucagon-like peptide 1 receptor agonists (GLP1) to improve glycemic control and reduce the high insulin demand." (PMID 33233602, 2020). "The expression of DPP4 was also accompanied with insulin resistance signals." (PMID 33267804, 2020). "It has been found that the upregulation of DPP-4 in mouse hepatocytes could lead to insulin resistance and obvious hepatic steatosis." (PMID 32368255, 2020). "Omarigliptin might also decrease DPP4 secretion by hepatocytes that might promote adipose inflammation and insulin resistance." (PMID 32211075, 2020). "Evidence exists in the literature that DPP4 has been identified as a novel protease playing crucial roles in the development of dyslipidemia, inflammation, and insulin resistance, all of which have been suggested to be involved in the pathogenesis of osteoporosis." (PMID 33312197, 2020). "AE subfractions attenuate DPP4 activation and the cascades of insulin resistance." (PMID 33267804, 2020). "To test our hypothesis, we correlated DPP4 activity with anthropometry, body composition variables, and insulin resistance markers in the pooled sample." (PMID 30886868, 2019). "Previously we reported dipeptidyl peptidase-4 (DPP-4) mediate insulin resistance signals, and Abelmoschus esculentus (AE) subfractions F1 (rich in quercetin glucosides and triterpene ester) and F2 (containing large amount of polysaccharides) attenuate DPP-4-mediated apoptosis." (PMID 31237881, 2019). "Given that DPP4 is a target of anti-diabetic therapies, this finding raises the intriguing possibility that BMAT-derived DPP4 might impact not only skeletal remodelling, but also systemic insulin resistance." (PMID 29888168, 2018). "Moreover, liver specific silencing of DPP4 lowered plasma insulin, improved glucose uptake, and suppressed insulin resistance in DIO mice." (PMID 30360455, 2018). "In addition to improvement of insulin resistance, DPP4 inhibitor ameliorated visceral adiposity via inhibition of adipogenesis by partial enhancement of energy expenditure along with metabolic changes in DIO-mice." (PMID 30279329, 2018). "Additionally, patients with high BMI or insulin resistance have been found to have high concentrations of serum DPP-4." (PMID 29435909, 2018). "DPP4 increases insulin resistance by enzymatically cleaving GLP-1." (PMID 30360455, 2018). "We also assessed whether the relationships of incretins and DPP-4 with insulin resistance (HOMA2-IR) and β-cell function (HOMA2-%B-C-peptide) in patients with RA differed from those in control subjects." (PMID 29041949, 2017). "In accordance with these findings, DPP-4 inhibition was reported to inhibit monocyte activation/chemotaxis and thereby lead to the improvement of atherosclerosis in a mouse model of atherosclerosis and insulin resistance." (PMID 28118775, 2017). "To evaluate the effect of a DPP-4 inhibitor as a treatment for diet-induced metabolic dysfunction in obese diabetic mice with severe insulin resistance, we also performed an 8-week study comparing db/db mice fed a diet consisting of SL or SO plus DPP-4 inhibitor." (PMID 26937254, 2016). "Collectively, the results of this investigation support the hypothesis that DPP-4 activation plays an important role in the development of aortic stiffness in female mice in the setting of WD-induced insulin resistance." (PMID 27391040, 2016). "Furthermore, DPP4 level on adipose tissue macrophage positively correlated with degree of insulin resistance." (PMID 26075284, 2015). "Furthermore, DPP-4 inhibitors are known to reduce insulin resistance and oxidative stress." (PMID 38256615, 2024).
Insulin resistance (continued). "The induction of IL-10 expression in the adipose tissue might promote Foxp3+ Treg expansion and suppress liver inflammatory cytokine expression and plasma DPP4 activity that may ultimately lead to mitigated insulin resistance and glucose intolerance in diabetic mice." (PMID 35883204, 2022). "Notably, we could also show that the use of DPP4 inhibitors was associated with a lower IGR and that metformin use was more prevalent in those with high insulin levels, indicative of insulin resistance." (PMID 36056607, 2022). "Moreover, treatment of DPP-4 inhibitor linagliptin revealed that, AE could prevent the hepatic lipogenesis, oxidative burden, and the related insulin resistance via downregulating DPP-4." (PMID 35290413, 2022). "The potential benefits of optimal egg-derived protein might be due to its metabolites, such as alpha-glucosidase inhibitory peptides, ACE inhibitory peptides, DPP-4 inhibitory peptides, which showed effects on the improvement of glucose tolerance, postprandial hyperglycemia, and insulin resistance." (PMID 35022027, 2022). "Our findings provide a new insight that the inhibition of M1 cytokine expression in adipose tissue with non-diabetic plasma may represent a novel therapeutic approach for attenuating DPP4 activity, systemic inflammation, and insulin resistance in diabetic patients." (PMID 34043673, 2021). "Although how DPP4 inhibitors affect cardiovascular (CV) outcomes remains uncertain, omarigliptin might confer CV benefits at least in part, via pleiotropic anti-inflammatory or anti-insulin resistance effects." (PMID 32211075, 2020). "Thus, the inhibition of DPP4 might induce body weight reduction via ameliorating inflammation and insulin resistance in adipocytes." (PMID 33173107, 2020). "However, it is still unknown whether the inverse relationship between triglyceride and glucose control is solely contributed to DPP-4 inhibitor treatment or due to drugs targeting on insulin resistance." (PMID 31485457, 2019). "Therefore, future studies should be conducted to confirm that DPP-4 inhibitor improves liver insulin resistance by suppressing inflammation and enhancing autophagy, focusing on the activity of GLP-1 and DPP-4 in both serum and tissues with different doses of sitagliptin treatment." (PMID 30123267, 2018). "The small size our sample might help justifying some of our findings, including the lack of association between DPP4 levels and markers of insulin resistance, for instance." (PMID 28450900, 2017). "Therefore, the insulin-resistance-improving effect of vildagliptin apparently enhances the fasting hypoglycemic effect and, furthermore, produces greater reductions in HbA1c levels than other DPP4 inhibitors." (PMID 25780477, 2015). "In summary, we have shown prospectively that increased fasting plasma DPP4 activity independently predict incident metabolic syndrome and insulin resistance in apparently healthy Chinese, and it may be considered as a novel marker of metabolic syndrome and insulin resistance." (PMID 24647445, 2014). "Since DPP4 is involved in the degradation of circulating active GLP-1 to biologically inactive fragments, plasma active GLP-1 level could also be associated with the development of insulin resistance and metabolic syndrome." (PMID 24647445, 2014). "Dipeptidyl peptidase-4 (DPP4) is a multifunctional protein with peptidase activity on substrates like GLP-1 and GIP, being involved in hyperglycemia, insulin resistance, dyslipidemia, oxidative stress, and inflammation." (PMID 40431452, 2025). "In fact, mice with hepatocyte-specific DPP-4 knockdown have a significant reduction in serum DPP-4 activity and reduced adipose tissue inflammation, insulin resistance, and glucose intolerance." (PMID 39054499, 2024). "Vildagliptin is an inhibitor of dipeptidyl peptidase-4 (DPP-4), an enzyme that degrades glucagon-like-peptide 1 (GLP-1), and has been used to rescue insulin resistance in pancreatic β-cells with lipid overload." (PMID 39897964, 2024).